ZMAT3 (zinc finger matrin-type 3)
Synonyms: PAG608; WIG1; MGC10613; FLJ12296; WIG-1
Tractability: Antibody: its Gene Ontology location is reachable by antibodies, with high confidence. PROTAC: ubiquitination databases record sites on it.
Gene: Protein-coding gene on chromosome 3 (178,960,121 to 179,072,323, reverse strand). Ensembl gene ENSG00000172667.
Subcellular location: Nucleus; Nucleus, nucleolus
Subcellular location (Human Protein Atlas): Nucleoplasm
Gene Ontology:
Molecular function: protein binding; RNA binding; nucleic acid binding; zinc ion binding
Cellular component: nucleoplasm; nucleus; nucleolus
Genetic constraint (gnomAD): Loss-of-function variants: 17 observed, 33.61 expected, observed/expected ratio (o/e) 0.51, 90% interval 0.34 to 0.76. The upper end of that interval is the gene's LOEUF score, 0.76, which puts it in group 3 of 6, group 1 being the genes least tolerant of losing a copy. Missense variants: 329 observed, 377.19 expected, observed/expected ratio (o/e) 0.87, 90% interval 0.8 to 0.96. Synonymous variants: 120 observed, 140.63 expected, observed/expected ratio (o/e) 0.85, 90% interval 0.74 to 0.99.
Homologues: Orthologues: chimpanzee ZMAT3 (100% identical), macaque ZMAT3 (98% identical), dog ZMAT3 (95% identical), guinea pig ZMAT3 (94% identical), pig ZMAT3 (93% identical), rabbit ZMAT3 (89% identical), rat Zmat3 (88% identical), mouse Zmat3 (87% identical), tropical clawed frog zmat3 (66% identical), zebrafish zmat3 (63% identical), Drosophila melanogaster dbf (20% identical), Drosophila melanogaster CG1231 (18% identical). Paralogues in human: ZNF385C (22% identical), ZNF385B (22% identical), ZNF385D (21% identical), ZNF385A (18% identical), ZMAT4 (17% identical), ZNF346 (13% identical), ZMAT1 (11% identical), ZMAT2 (8% identical), KRCC1 (2% identical).
Diseases named in the same sentence as ZMAT3 in open-access papers:
ZMAT3 is named in the same sentence as 46 diseases in open-access papers, as found by Europe PMC text mining. Sharing a sentence is not in itself a finding about the gene and the disease. The quoted sentences say what the papers report.
leukaemia (4 papers, 2020 to 2024). "From this approached also Zmat3 was implicated in development of lymphoma/leukaemia, but only when also Puma and Cdkn1a were depleted." (PMID 34362419, 2021).
lymphoma (4 papers, 2021 to 2025). A malignant (clonal) proliferation of B- lymphocytes or T- lymphocytes which involves the lymph nodes, bone marrow and/or extranodal sites. "Lymphoma burden, as determined by thymus weight, was smaller in p21−/−Zmat3−/− mice compared to those detected in Zmat3−/−, p21−/− and wt mice." (PMID 38110554, 2024). "The majority of sick Puma−/−Zmat3−/− and Puma−/−p21−/−Zmat3−/− mice presented with lymphoma as determined by histopathological analysis, while most sick Zmat3−/−p21−/− mice presented with solid tumours." (PMID 38110554, 2024). "Immunophenotyping of the tumours from sick p21−/−Zmat3−/−, Zmat3−/− and p21−/− mice confirmed that these lymphomas were all of T lymphoid origin expressing THY1 and variable expression of CD4 and CD8." (PMID 38110554, 2024). "Notably, Puma−/−Zmat3−/− and Puma−/−p21−/−Zmat3−/− mice presented with lymphoma, and Zmat3−/−p21-/ mice mainly developed solid tumours (6/8)." (PMID 38110554, 2024).
liver cancer (3 papers, 2022 to 2025). An epithelial or non-epithelial malignant neoplasm that arises from the liver. "To determine if ZMAT3 inhibits HKDC1 expression in multiple cell lines, we performed RT-qPCR after ZMAT3 knockdown in SW1222 (CRC cells), HCEC-1CT (immortalized human colonic epithelial cells), and HepG2 (liver cancer cells)." (PMID 40391325, 2025).
lung adenocarcinoma (3 papers, 2020 to 2024). A carcinoma that arises from the lung and is characterized by the presence of malignant glandular epithelial cells. "Of note, CRISPR/Cas9-mediated loss of ZMAT3 enhanced tumorigenesis in autochthonous mouse models of lung adenocarcinoma and hepatocellular carcinoma." (PMID 38110554, 2024). "Taken together, we conclude that in the context of c-MYC-driven lymphomagenesis or mutant KrasG12D-driven lung adenocarcinoma development, additional co-occurring mutations are required to resolve Zmat3 tumor suppressive activity." (PMID 33082333, 2020). "TP53INP1, IGF1 and ZMAT3 were differentially expressed in clinical samples of lung adenocarcinoma with BM, while miR-106a and TP53INP1 showed a significant negative correlation." (PMID 34718338, 2021). "Here, to investigate which oncogenic drivers co-operate with Zmat3 loss to promote neoplastic transformation, we utilized Zmat3 knockout mice in models of c-MYC-driven lymphomagenesis and KrasG12D-driven lung adenocarcinoma development." (PMID 33082333, 2020).
breast carcinoma (2 papers, 2022 to 2024). "Focusing on individual genes, our multivariate COX regression analysis identified ZMAT3 and XG as independent prognostic risk factors for breast cancer, with ZMAT3 having the highest HR value." (PMID 39664194, 2024). "Contrary to previous reports, we found that ZMAT3 is an independent risk factor for poor prognosis in breast cancer, with patients exhibiting high levels of ZMAT3 expression having significantly lower OS compared to those with low expression levels." (PMID 39664194, 2024). "Multivariate Cox regression analyses in the TCGA dataset showed that XG and ZMAT3 were independent prognostic risk factors for breast cancer, and ZMAT3 had higher HR values, suggesting that it may be a key gene influencing the prognosis of breast cancer." (PMID 39664194, 2024). "When we used siRNA transfection to reduce ZMAT3 expression in breast cancer cells, the proliferation and invasion capabilities of these cells were significantly inhibited." (PMID 39664194, 2024). "Given that the attenuation of ZMAT3 expression diminished the proliferative and invasive propensities of breast cancer cells, we evaluated the sensitivity of ZMAT3 to a spectrum of pharmacological compounds." (PMID 39664194, 2024). "Transfection of siRNAs targeting ZMAT3 was performed in MDA-MB-231 and MCF-7 cells to investigate the regulatory role of ZMAT3 expression in breast cancer cell progression.Western blot confirmed that ZMAT3 was successfully knocked down." (PMID 39664194, 2024). "Kaplan-Meier curves show that SDC1, NACAD, ZMAT3, CCND2, XG and SGCE are associated with prognosis in breast cancer patients." (PMID 39664194, 2024). "The role of ZMAT3 in the development and progression of breast cancer also warrants further experimental investigation." (PMID 39664194, 2024). "The mRNA expression level of ZMAT3 in human breast cancer cell lines MDA-MB-231 and MCF-7 was significantly lower than that in human breast epithelial cell line MCF-10A." (PMID 39664194, 2024). "In the 31 pairs of clinical samples we collected, ZMAT3 expression levels were significantly lower in breast cancer tissues compared to adjacent normal tissues." (PMID 39664194, 2024). "Additionally, knockdown of ZMAT3 significantly inhibited the invasion and migration ability of breast cancer." (PMID 39664194, 2024). "Finally, we validated ZMAT3 expression levels clinically and confirmed its relevance in breast cancer using CCK-8 and migration assays." (PMID 39664194, 2024). "Overall, our findings indicated that ZMAT3 may promote the proliferation and invasion of breast cancer." (PMID 39664194, 2024). "Developing inhibitors or small molecule drugs against ZMAT3 could provide new treatment options for breast cancer patients, especially those with high ZMAT3 expression and poor prognosis." (PMID 39664194, 2024). "However, in cancer, the senescence mechanism may be exploited by cancer cells to evade apoptosis, which could be one of the mechanisms by which high ZMAT3 expression promotes breast cancer progression." (PMID 39664194, 2024). "Silencing the ZMAT3 gene in the TSPRS significantly reduced the proliferation and invasiveness of breast cancer cells." (PMID 39664194, 2024). "Furthermore, ZMAT3 could serve as a potential target for targeted therapy in breast cancer." (PMID 39664194, 2024). "To date, no studies have reported on the role of ZMAT3 in breast cancer." (PMID 39664194, 2024).
colorectal cancer (2 papers, 2024 to 2025). A primary or metastatic malignant neoplasm that affects the colon or rectum. "We chose to focus on HKDC1 because by quantitative proteomics, HKDC1 was the most strongly up-regulated protein in ZMAT3-depleted colorectal cancer (CRC) cells." (PMID 40391325, 2025). "Using quantitative proteomics, we identified HKDC1 as the most significantly upregulated protein in ZMAT3-depleted colorectal cancer cells." (PMID 40391325, 2025). "For instance, in colorectal cancer, silencing ZMAT3 can promote the proliferation of cancer cells by increasing the inclusion of CD44 variant exons." (PMID 39664194, 2024).
cervical cancer (1 paper, 2014). A primary or metastatic malignant neoplasm involving the cervix.
depression (1 paper, 2023). "The results of a recent study indicate that ZMAT2, a gene from the same family as ZMAT3, is a significant transcriptome-wide risk gene for depression and shows a strong association with depression in the brain expression quantitative loci data set." (PMID 37547246, 2023).
dermatitis (1 paper, 2019). An inflammatory process affecting the skin. "In this prospective cohort study, we found that symptoms of dermatitis radiation, pain, pruritus and fatigue were associated with the expression level of some genes of the DNA-damage response pathway (FDXR, SESN1, XPC, ZMAT3, ATM, BCL2/BAX, and CDKN1A)." (PMID 31632918, 2019). "While the expression level of FDXR gene increased in patients experiencing a high grade of dermatitis radiation, those of SESN1, ATM, XPC, ZMAT3, CDKN1A genes decreased when radiation toxicity was manifested." (PMID 31632918, 2019).
diabetes (1 paper, 2022). "To directly demonstrate whether ZMAT3 enhanced expression causes senescence in human preadipocytes, we transfected the pCMV6‐ZMAT3 construct in APC from donors with no diabetes familiarity." (PMID 35146866, 2022). "In previous methylome comparison in APC from FDR and individuals with no diabetes familiarity (CTRL), ZMAT3 emerged as one of the top‐ranked senescence‐related genes featuring hypomethylation in FDR and associated with T2D risk." (PMID 35146866, 2022).
Down syndrome (1 paper, 2022). "In addition, ZMAT3 hypomethylation has been found in the cerebellum of subjects with Down Syndrome, which has been described as a human condition of accelerated aging." (PMID 35146866, 2022).
follicular thyroid cancer (1 paper, 2023). "Of note, ZMAT3 induction by the erytropoietin/erytropoietin receptor (Epo/EpoR) axis was reported in the papillary thyroid cancer subtype but not in others as anaplastic and follicular thyroid cancer." (PMID 37372430, 2023).
Obesity (1 paper, 2025). Accumulation of substantial excess body fat. "When adjusting for both sex and chronological age, we observed that GLB1 and ZMAT3 expression remained significantly elevated in the subjects with obesity (Sup." (PMID 40127780, 2025). "Moreover, the identification of ZMAT3 as a novel senescence marker provides a potential valuable tool for future research and clinical applications aimed at targeting SkM senescence to prevent age- and obesity-related metabolic diseases." (PMID 40127780, 2025). "Adjusting for sex alone did not alter the significant upregulation of GLB1, ZMAT3, CDKN1A, and CDKN2A in individuals with obesity (Sup." (PMID 40127780, 2025).
Pruritus (1 paper, 2019). Pruritus is an itch or a sensation that makes a person want to scratch. "Symptoms of pruritus resulted associated at t1 with a 0.79-fold change of XPC and with a 1.01-fold change of ZMAT3; at t2 pruritus was associated with a 0.87-fold change of ATM, and a lower BCL2/BAX ratio (respectively, 0.76- vs. 1.15-fold change)." (PMID 31632918, 2019).
thymic lymphoma (1 paper, 2024). "We found that p21−/−Zmat3−/− as well as Zmat3−/− and p21−/− mice developed thymic lymphoma at a similar rate to wt mice." (PMID 38110554, 2024).
ZIKV infection (1 paper, 2017). "One recent study reported that several apoptotic regulators, including ZMAT3, PMAIP1, TNFRSF10D, BBC3, were upregulated, and cell cycle genes, such as E2F1 and E2F2, were downregulated after ZIKV infection." (PMID 29116029, 2017).
tumor (30 papers, 2009 to 2026). "It was found that GABRB2 and ZMAT3 mRNA expressions are up-regulated in PTC compared to tissue adjacent to the tumor, and that GABRB2 mRNA expression is associated with the best survival in PTC, suggesting its potential usefulness as a prognosis marker." (PMID 37372430, 2023). "Recent studies suggest that ZMAT3 significantly contributes to the tumor suppressive effects of p5317,18." (PMID 40391325, 2025). "In vivo studies in mice have demonstrated that Abca1, Gls2, Mlh1, Padi4 and Zmat3 play key roles in mediating the tumor suppressor effects of p5312–15." (PMID 40391325, 2025). "Amongst the hits identified in these screens, the RNA binding protein ZMAT3 was found to be a potent tumour suppressor." (PMID 38110554, 2024). "Focusing on the top 60 perturbations with robust P60 or tumour coverage, we observed that Zmat3, Prkdc, Myh8, Kdr, Dnah3 and Ahnak showed the highest positive selection rates." (PMID 39020166, 2024). "We were interested to further investigate the role of ZMAT3 in tumour suppression beyond the haematopoietic system." (PMID 38110554, 2024).